ACE (angiotensin I converting enzyme)
Diseases named in the same sentence as ACE in open-access papers (continued):
Sharing a sentence is not in itself a finding about the gene and the disease.
heart failure (continued). "The composite outcome of cardiovascular death, first hospitalization for heart failure, and first outpatient episodes of symptomatic heart failure was not significantly different between the ARNI and ACE inhibitor groups." (PMID 36101398, 2022). "While combination therapy of ACE inhibitor with ARB is not widely used, there is precedent for combination therapy for heart failure, renal disease, and among aged individuals." (PMID 35359831, 2022). "In another study, it was observed in an animal model of heart failure that APT normalized ACE2 and reduced ACE in plasma but did not change in the soleus and plantaris muscle." (PMID 34229719, 2021). "We suggest it is supportive to take delicate individualized combination therapy including ACE inhibitor and inotropic agents for cardiomyopathy in DMD patients with EF < 45%, rather than usual heart failure therapy." (PMID 33266491, 2020). "On the other hand, it has been recently shown that treatment with ACE inhibitors and ARBs does not increase ACE2 plasma levels in patients with heart failure." (PMID 33195473, 2020). "Whereas ARBs produce angioedema with an incidence approximately half that of ACE inhibitor therapy in patients without heart failure, LCZ696 produces angioedema with an incidence at least equal to that of ACE inhibitor therapy." (PMID 30283782, 2018). "Beta–blockers are recommended for treatment of all patients with stabile heart failure from ischemic or non-ischemic etiology and reduced left ventricular ejection fraction in NYHA Class II to IV, as a standard therapy, including ACE-inhibitors and diuretics." (PMID 27275338, 2016). "The administration of candesartan in the CHARM trial (Candesartan in Heart Failure–assessment of reduction in mortality and morbidity) in patients with CHF who did not tolerate ACE inhibitors led to a 23% reduction in cardiovascular mortality and hospital days." (PMID 39062156, 2024). "Patients with ATTR-CM require management of heart failure symptoms, but ARBs, ACE inhibitors, and beta-blockers are not widely used in ATTR-CM compared to other heart failures because patients with ATTR-CM do not tolerate these drugs well due to the presence of hypotension." (PMID 35840997, 2022). "In fact, in ELITE (Evaluation of Losartan in the Elderly study), VALIANT (VALsartan In Acute myocardial iNfarcTion), VAL-HEFT (Valsartan Heart Failure Trial) and CHARM (Candesartan in Heart failure - Assessment of moRtality and Morbidity), ARB were never superior to ACE inhibitors." (PMID 26637405, 2016). "Furthermore, unlike chymase inhibitors, ACE inhibitors and ARBs currently in clinical use do not inhibit the activation of TGF-β and MMP-2, suggesting that chymase could serve as a novel therapeutic target for cardiac remodeling in conditions such as heart failure." (PMID 40943161, 2025).
COVID-19 (802 papers, 2020 to 2026). A disease caused by infection with severe acute respiratory syndrome coronavirus 2. "Because ACE-2 may be modulated by angiotensin-converting enzyme inhibitors (ACEIs) and angiotensin II receptor blockers (ARBs), there is concern that patients treated with ACEIs and ARBs are at higher risk of coronavirus disease 2019 (COVID-19) pneumonia." (PMID 33347477, 2020). "FXR/RXR, DPP4, JAK2, and ACE are associated with COVID-19, while CNGA1, BLT1, COX2, and 5-LOX are linked to pharyngitis." (PMID 40076279, 2025). "Three of these studies showed that increasing levels of ACE were positively and significantly associated with COVID-19,31,48,49 with the risk of infection, hospitalization, and severity increasing by 11%–63%." (PMID 39449666, 2025). "Several studies shave demonstrated strong associations between ACE-insertion/deletion (I/D) and COVID-19." (PMID 39194697, 2024). "The results of this study showed that serum PTX3 levels and ACE I/D polymorphism are important predictors of severity of COVID-19 lung infiltrates." (PMID 39062191, 2024). "There are many factors affecting susceptibility to COVID-19, including allergies and asthma, human leukocyte antigen (HLA), angiotensin converting enzyme (ACE), ABO blood type, etc." (PMID 38241306, 2024). "In conclusion, overall data support that vitamin D sufficiency, ACE inhibitors, and ARBs reduce the risk of COVID-19, associated complications, and deaths." (PMID 39452140, 2024). "The results of this study showed that the serum levels of PTX3 and ACE I/D polymorphism play a significant role in COVID-19 CXR severity." (PMID 39062191, 2024). "Previous studies have shown a strong relationship between the D allele of the ACE I/D polymorphism, clinical severity, and outcome of COVID-19." (PMID 39062191, 2024). "The association of soluble ACE activity and COVID-19 severity is also controversial since both unaltered and decreased activity were reported in severe patients in different studies." (PMID 38543635, 2024). "This I/D polymorphism affects the levels of ACE, the deletion being associated with more severe forms and adverse outcomes in various conditions, including COVID-19." (PMID 37284379, 2023). "Further investigation is required to explore the potential beneficial role of the I/D polymorphism of ACE in the development of COVID-19 vaccines." (PMID 38058963, 2023). "This meta-analysis was the first to summarize the existing data regarding the relation of ACE I/D polymorphism with COVID-19 susceptibility, which included 8 articles recruiting 1362 COVID-19 patients together with 4312 controls." (PMID 38058963, 2023). "Present study compared the ACE II/DD genotype polymorphism between COVID-19 patients and their healthy contacts who lived with them during the epidemic time." (PMID 37284379, 2023). "HT and DM, which are associated with unfavorable outcomes in patients with COVID-19, are closely correlated with increased activation of the ACE/Ang 2 axis." (PMID 37432962, 2023). "The association of the ACE rs1799752 variant with COVID-19 severity has been observed in different reports." (PMID 37108839, 2023). "The results indicated, for the first time in the literature, a genetic protection factor for the susceptibility to the worsening of COVID-19, which was mediated by the combined polymorphisms of ACE and ACE2." (PMID 38032879, 2023). "There are reports that statins and angiotensin-converting enzyme (ACE) inhibitors/angiotensin II receptor blockers (ARBs) have reduced the risk of COVID-19 severity." (PMID 37542210, 2023). "ACE deletion polymorphism was recently reported to be associated with susceptibility to COVID-19 in a risk-dependent manner among the Chinese population." (PMID 36916970, 2023). "Regarding ACE, different reports have linked ACE variants and their expression with COVID-19 mortality and severity among worldwide populations." (PMID 37108839, 2023).
COVID-19 (continued). "As revealed by subgroup analysis stratified by COVID-19 type, ACE D allele showed significant relation with the higher COVID-19 severity." (PMID 38058963, 2023). "More and more reports have shown that SARS-CoV-2 plays a pathogenic role in COVID-19 patients through binding to the angiotensin-converting enzyme (ACE) 2 receptor." (PMID 37415112, 2023). "Actually, it is difficult to reveal the association between the level of ACE enzyme and gene polymorphism in COVID-19 patients, as it is a hyperinflammatory state." (PMID 37432962, 2023). "The data suggest that the use of different antihypertensive treatments in the population plays an important role: the risk of developing a severe form of COVID-19 was lower in patients treated with ACE inhibitors." (PMID 36963083, 2023). "In conclusion, our study demonstrated that the ACE-2 rs908004 genotype and allele as well as ACE-1 rs4343 allele can be a predictive factor for COVID-19 severity and treatment response in Egyptian patients." (PMID 37426824, 2023). "As revealed by subgroup analysis stratified by COVID-19 type, ACE D allele showed a significant association with higher COVID-19 severity." (PMID 38058963, 2023). "ANPEP and ACE are two genes that have been implicated in COVID-19 due to their involvement in the renin-angiotensin-aldosterone system (RAS)." (PMID 38813031, 2023). "Functional interference with ACE-2 and altered homeostatic regulation of ACE and ACE-2 functions have been proposed as a possible risk modifier of COVID-19 clinical progression." (PMID 37515136, 2023). "There is evidence that ACE inhibitors/ARBs use was associated with a significantly decreased risk of COVID-19 mortality." (PMID 36908454, 2023). "We demonstrated that elevated levels of ACE are a risk factor for poor prognosis in COVID-19 and analyzed the predictive value and importance for worsening of disease." (PMID 37432962, 2023). "We investigated the relationship between COVID-19 progression and genetic variants in both ACE-2 and IFITM-3." (PMID 38155729, 2023). "This study also reported an association between ACE gene polymorphism and disease severity, where the ACE II genotype was found to be protective against severe COVID-19." (PMID 37432962, 2023). "Further studies with larger sample size are needed, to finalize the role of the I/D polymorphism in not only COVID-19 but also other disorders involving the ACE gene." (PMID 37284379, 2023). "For instance, the rs1799752 ACE has been associated with COVID-19 risk and ACE expression and with the ACE2 protein levels in alveolar lung epithelium in patients with the disease." (PMID 37108839, 2023). "This meta-analysis was the first to summarize existing data regarding the association of the ACE I/D polymorphism with COVID-19 risk, which included 8 articles with 1362 COVID-19 patients together and 4312 controls." (PMID 38058963, 2023). "These mutations make this COVID-19-causing virus highly infective by increasing affinity for the Angiotensin-Converting Enzyme (ACE)-2 receptors." (PMID 36518355, 2022). "ACE DD genotype is strongly associated with increased disease severity of COVID-19 and is also linked with high COVID-19 mortality." (PMID 35371838, 2022). "Previous studies reported that treatments with ACE inhibitors and angiotensin II receptor blockers were associated with a lower risk of death in COVID-19 patients." (PMID 36439253, 2022). "ACE insertion/deletion polymorphisms (rs4646994 and rs179752) have also been linked to COVID-19 severity." (PMID 35885894, 2022). "In COVID-19 patients with underlying CV illness and ACE inhibitors (ACEi)/ARB medication, it was suggested that elevated ACE2 would encourage SARS-CoV-2 infection and replication." (PMID 35408447, 2022). "Angiotensin receptor blockade has been postulated to increase surface ACE2 expression, raising concern for potential increased COVID-19 risk for patients on ACE inhibitors or angiotensin receptor blockers." (PMID 35231079, 2022).
COVID-19 (continued). "The purpose of this study was to see if a correlation exists between Angiotensin I Converting Enzyme (ACE) insertion/deletion (I/D) polymorphism and the severity of COVID-19 patients’ symptoms." (PMID 36531237, 2022). "In contrast, severe COVID-19 patients persistently treated with an ACE inhibitor/Angiotensin II receptor blocker had a higher risk of acute renal damage compared to the 149 individuals from the Referral Center Cohort in the northeast of France." (PMID 36363511, 2022). "The possible association between the ACE genotype and the severity of COVID-19 should be further explored." (PMID 36519165, 2022). "Considering that the increase in ACE2 activity was related to organ injury and infectivity in patients with COVID-19, OSA increases the risk of COVID-19 in patients included in this study via the ACE mechanism." (PMID 33407347, 2021). "The deleterious activities of RAS within the COVID-19-infected cohorts can be further amplified by the presence of genetic polymorphism in the angiotensin-converting enzyme (ACE)." (PMID 32901433, 2021). "Pharmacological inhibition of ACE and angiotensin II can reduce the risk of mortality in COVID-19 patients." (PMID 34943795, 2021). "An emerging example of this important parallel is ACE2 pathway drugs (ACE inhibitors and angiotensin receptor blocking drugs), which are increasingly observed in humans with COVID-19 to be associated with improved survival advantage." (PMID 34071060, 2021). "The study objective was to describe a biological framework associating ethnic prevalence of ACE deletion polymorphism to COVID-19 comorbidities providing rationale for therapeutic utility of ACE-I/ARBs to improve outcomes." (PMID 32901433, 2021). "Due to the well-characterized role of ACE2 in SARS-CoV-2 infection, we generated novel information regarding the molecular and phenotypic characteristics of ACE gene network in the context of their potential involvement in COVID-19 susceptibility." (PMID 34512723, 2021). "Controlled experimental studies have suggested that the ACE polymorphisms also affect the mortality rates in COVID-19." (PMID 34803443, 2021). "To further explain the molecular mechanism of this polymorphism correlation, we investigated genotype-specific ACE activity, cytokine expression, and immune response from a large cohort with hundreds of COVID-19 patients." (PMID 35095487, 2021). "Increased prevalence in frequency of the ACE polymorphism within ethnic groups, in part, is likely responsible for the observed severity of COVID-19 comorbidities and mortality in this population." (PMID 32901433, 2021). "Despite some controversies, numerous studies have reported a significant association between the use of ACE inhibitors and reduced risk of COVID-19." (PMID 34769093, 2021). "We noticed that all tested patients had multiple polymorphisms and, in particular, a significantly higher prevalence of ACE D/D polymorphism in severe COVID-19 patients." (PMID 34441050, 2021). "A recent cohort study showed that the use of ACE inhibitors or ARBs was associated with significantly improved survival in patients with hypertension hospitalized with COVID-19." (PMID 33025384, 2021). "The log-transformed prevalence (R2 = 0.410; p < 0.0001) and mortality (R2 = 0.457; p < 0.0001) for COVID-19 in 33 countries (on April 1, 2020) negatively correlated with ACE-1 D allele frequency, taking into account the start of the epidemic in each country." (PMID 34399734, 2021). "The presence of ACE DD polymorphism with COVID-19 infection likely augments ACE/Ang-II activities, increasing severity of COVID-19 morbidities and impacts outcomes." (PMID 32901433, 2021). "The ACE polymorphism has been reported to be associated with cytokines such as IL-6, IL-8, and IL-10, which are biomarkers of severe COVID-19 patients." (PMID 35095487, 2021). "Regression analysis correlated presence of ACE insertion/deletion (I/D) polymorphism to COVID-19 incidence and mortality." (PMID 32901433, 2021).
COVID-19 (continued). "As well, the effect of ACE D/I biallelic polymorphism on COVID-19 severity in CF should be considered in future studies." (PMID 34016096, 2021). "This has led the researchers to further investigate the relationship between COVID-19 and ACE gene polymorphisms." (PMID 34603503, 2021). "The ABO gene locus was previously known as a source of pharmacogenomic variants correlated to ACE activity; most strikingly, now the exact same genetic locus has been implicated in increased respiratory failure of COVID-19 patients." (PMID 33323946, 2021). "The same research group published a similar research that did not confirm the potential risk of angiotensin-converting enzyme (ACE) inhibitor or angiotensin II receptor blockers (ARBs) for in-hospital COVID-19 patients." (PMID 34025393, 2021). "In conclusion, our data indicate that subjects taking ACE inhibitors have an increased risk of urticaria/angioedema after vaccination with the BNT162b2 mRNA COVID-19 vaccine." (PMID 34579248, 2021). "Regarding polymorphisms in ACE2 gene itself, it is known that variants in this genetic locus promote pharmacogenetic modulation of ACE inhibitors response and therefore they have now been under scrutiny as genetic susceptibility loci for COVID-19 outcomes." (PMID 33323946, 2021). "When directly comparing invididuals prescribed ACE inhibitors with those prescribed ARBs, there was a higher risk of COVID-19 diagnosis in the latter." (PMID 33722197, 2021). "All encompassed studies showed that hypertensive patients with COVID-19 who received ACE inhibitor or ARB in hospital treatment were associated to lower risk of all-cause mortalities compared to the non-users." (PMID 33544293, 2021). "We chose the angiotensin-converting enzyme (ACE) gene, encoded as ACE, which has 40% overall identity to ACE-2 and is positively related to COVID-19." (PMID 34209818, 2021). "The second viewpoint is that ARB and ACE inhibitors enhance vasodilation and anti-inflammatory effects for COVID-19 patients, which is of importance due to associations between Ang II and reactive oxygen species (ROS)." (PMID 33801921, 2021). "It has been long debated if the use of ACE inhibitors in COVID-19 patients or at risk of infection increases the risk of poor outcome, given the rationale that SARS-CoV-2 uses the ACE2 receptor to entry into target cells." (PMID 33514012, 2021). "ACE polymorphism with regard to the COVID-19 outcome seems to be affected by the presence of ACE1 D/I polymorphism." (PMID 34603503, 2021). "In contrast, the frequencies of DD, DI, and II genotypes of ACE in the COVID-19 patients were 40%, 53%, and 7%, respectively; the D allele frequency was 67%, and the I allele frequency was 33%." (PMID 34603503, 2021). "To further elucidate the influence of the ACE expression level on susceptibility to COVID-19, we reanalyzed the retrospective lung data." (PMID 35095487, 2021). "The second study claimed to negate the association of ACE inhibitors and angiotensin-receptor blockers (ARBs) with in-hospital COVID-19 deaths." (PMID 33912030, 2021). "The aim of this study is to assess the impact of ACE gene polymorphism on the susceptibility and clinical outcomes of COVID-19." (PMID 34603503, 2021). "The association of ACE inhibitors/ARBs with decreased mortality in cohorts of COVID-19 patients, along with their proposed mechanism in reducing viral entry in vitro, has prompted a number of RCTs on the effect of these therapeutics in COVID-19 patients." (PMID 34061779, 2021). "In the present study we investigated the association of rs4341 and rs4343 polymorphisms of the ACE gene with COVID-19 outcomes in patients with different degree of severity." (PMID 34489863, 2021). "The distribution of ACE gene polymorphisms and their impact on the outcomes of 112 COVID-19 patients are studied in this present research." (PMID 34603503, 2021).